THBS1 (thrombospondin 1)
Diseases named in the same sentence as THBS1 in open-access papers (continued):
Sharing a sentence is not in itself a finding about the gene and the disease.
tumor (continued). "Finally, THBS1, or Thrombospondin-1, is a multifunctional protein that not only acts as an endogenous inhibitor of angiogenesis, but also promotes tumor invasion, metastasis, and immune response in the tumor environment." (PMID 40427760, 2025). "Moreover, tumour cells could increase THBS1 expression significantly in fibroblasts in ex vivo co‐culture assays, indicating that THBS1 was critical for fibroblast activation." (PMID 38778448, 2024). "Therefore, fibroblastic stromal cells may also have anti-leukemic functions, as demonstrated here for THBS1, similar to some of the tumor-suppressive functions of myCAF in solid cancers." (PMID 36899005, 2023). "Furthermore, YY1 also promotes tumor angiogenesis by activating the transcription of VEGF while suppressing anti-angiogenic factors such as thrombospondin-1 (TSP-1), pigment epithelium-derived factor (PEDF), and tissue inhibitor of metalloproteinase 2 (TIMP-2)." (PMID 37444616, 2023). "Therefore, we hypothesized that Let-7i-5p may contribute to tumor growth by suppressing the expression of THBS1 and lowering TSP1 levels." (PMID 37829341, 2023). "However, consistent with the recent literature and our analysis of human tumours, at later stages of tumorigenesis, the fitter mutant cells outcompete WT cells, as shown by the decrease in cells expressing both THBS1 and nuclear YAP in advanced human adenocarcinomas." (PMID 35543624, 2022). "However, the pro-lymphangiogenic effects of these proteins seem to be tumor-specific, as THBS1 and PEDF may dampen tumor lymphangiogenesis in colorectal and prostate cancers." (PMID 35887583, 2022). "IGFBP3 could inhibit angiogenesis by upregulating THBS1, leading to tumor growth arrest." (PMID 34824343, 2021). "Moreover, THBS1 is a secreted protein that acts in the tumor microenvironment to inhibit angiogenesis, regulate antitumor immunity, tumor cell migration, and influence the activities of extracellular proteases and growth factor, which plays an important role in tumor progression." (PMID 33912465, 2021). "Similarly, with regard to tumor cell invasion, the function of THBS1 is complex and controversial, and may vary by cell type, tissue type, and subcellular localization." (PMID 34635636, 2021). "Furthermore, thrombospondin-1 (TSP-1) MKC status might be an interesting marker as to predict tumor progression." (PMID 32218149, 2020). "used a SGC cell line (OCUM-2MLN) and showed that disruption of TGFβ signaling in SGC may accelerate tumor growth through upregulated tumor angiogenesis that is induced by decreased expression of THBS1 after inhibition of TGFβ signaling by dominant-negative TGFBR." (PMID 33178597, 2020). "Thus, while endothelial cells of the sprouting neovasculature were shown to foster metastatic outgrowth, those of stable microvasculature mostly preserved and promoted cancer cell dormancy through the tumor suppressor thrombospondin-1, acting as a rate-limiting step for disease re-occurrence." (PMID 33193295, 2020). "Serum and intratumoral levels show conflicting associations with patient outcome, which may reflect differences in the release of thrombospondin-1 from the tumor microenvironment into the systemic circulation, or its specific localized effects within the tumor environment." (PMID 33014869, 2020). "Accumulating evidences have suggested that Thrombospondin-1 (THBS1) may affect tumor immunity." (PMID 33274204, 2020). "Furthermore, tumour cell-bound CD47 is important for THBS1 activity in tumour cell invasion." (PMID 30850588, 2019). "Additionally, THBS1 is expressed in tumor cells, showing tumor progressive function." (PMID 31580518, 2019). "As a member of this family, thrombospondin-1 (THBS1) (also known as TSP1) is the first identified endogenous antiangiogenic factor that might suppress tumor growth through inhibiting tumor angiogenesis that is a critical process in cancer pathogenesis and treatment." (PMID 31847842, 2019).
tumor (continued). "Besides, the tumor volume and weight of mice inhibited by over-expression of THBS1 could be eliminated by over-expression of BZRAP1-AS1 (p < 0.05)." (PMID 31847842, 2019). "Thus, the pathological roles and clinical significance of THBS1 may depend on the nature of the model and on the stage of tumor progression." (PMID 25051363, 2014). "THBS1 expression does not appear to be associated with tumor growth properties." (PMID 24195060, 2013). "Other mechanisms of THBS1 regulation may include epigenetic modulation via histone modifications, transcriptional repressors and enhancers that augment or inhibit binding and activity or regulation via other tumor-suppressor genes." (PMID 24195060, 2013). "Accordingly THBS1 regulation may be an important part of the tumor suppressor function of FLCN." (PMID 20573232, 2010). "scRNA-seq identified cancer-associated immune signatures, notably consistent upregulation of THBS1 and CH25H, indicative of systemic imprinting by tumour-derived cues." (PMID 42308424, 2026). "CD36 attenuates angiogenesis by binding to thrombospondin-1 (TSP-1) and thereby inducing apoptosis or blocking the vascular endothelial growth factor receptor 2 pathway in tumor microvascular endothelial cells." (PMID 41011284, 2025). "The resulting axis induces ROS production by neutrophils and the formation of NETs, which degrade thrombospondin-1 (TSP-1) and promote metastatic tumor cell growth in the lung." (PMID 41019086, 2025). "Functionally, these pathways are known to enhance tumor cell migration and invasion through WNT5A-LRP6/FZD3 and THBS1-ITGAV ligand-receptor signaling pathways." (PMID 41450739, 2025). "Among these known mediators, THBS1 and BMP6 were also found in our in vitro screen for tumor cell dormancy-inducing endothelial factors, reinforcing our confidence in the validity of our screening methodology." (PMID 41185039, 2025). "Using three spatially-enriched marker genes for each tumor subregion (CT: BCAN, CSPG5, TOP2A; Pseudo: HILPDA, IGFBP5, LGALS3; and MVP: MGP, LUM, THBS1) we identified distinct sub-populations of malignant cells from the scRNA-seq data." (PMID 41366031, 2025). "Collectively, these results indicate that RBMX knockout in tumor cells boosts CD8+T cell activity by promoting H2-K1 and inhibiting THBS-1 expression." (PMID 40941025, 2025). "THBS1 also promoted proliferation and inhibited apoptosis in RAW264.7 cells and promoted tumour cell proliferation, migration, growth, and survival in vivo." (PMID 39796249, 2025). "Upregulation of thrombospondin 1 (THBS1), THBS2, and pigment epithelium–derived factor (PEDF) in tumor tissues creates a soluble anti-angiogenic environment that suppresses blood vessel formation while promoting lymphangiogenesis." (PMID 41296409, 2025). "Similarly, thrombospondin 1 (THBS1), a secreted protein, is responsible for inhibiting angiogenesis, regulating antitumor immunity, stimulating tumor cell migration, and modulating the activity of extracellular proteases and growth factors in the tumor microenvironment." (PMID 39941831, 2025). "While THBS1 and THBS2 also directly promote iCCA cell proliferation, adhesion and motility, in the present research we demonstrated that PEDF exhibits a tumor suppressor activity on iCCA cell lines by inhibiting their migration and invasion." (PMID 40001923, 2025). "THBS1 can modulate innate and adaptive immune cells through a CD47-dependent mechanism, restricting anti-tumor immune responses." (PMID 41174721, 2025). "On one hand, primary CRC tumors harbor MHC-low TAMs with impaired antigen presentation, liver metastases are enriched with THBS1+ MHC-low TAMs that express pro-angiogenic factors and genes like THBS1 and MARCO, supporting tumor progression." (PMID 41450739, 2025). "Although THBS1 and THBS2 directly affect iCCA tumor cells by enhancing their malignant traits, the direct role of PEDF in iCCA cells remains unexplored." (PMID 40001923, 2025).
tumor (continued). "In GBM, expression of THBS1 is transcriptionally regulated via the TGF-β/SMAD3 axis and enriched at the invasive tumor margins." (PMID 40885689, 2025). "Some of the genes, such as THBS1, CXCL14, and DMBT1, were notably enriched in AS_EP_STAS, suggesting their crucial role in the process of tumor cell spread into air spaces." (PMID 40786043, 2025). "Increasing influenza virus titres and reducing tumour formation in MDCK cells are issues that must be addressed; however, our findings indicate that THBS1 plays a role in regulating MDCK cell proliferation and apoptosis through TGF-β/Smad signalling." (PMID 39796249, 2025). "In the iCCA, PEDF along with THBS1 and THBS2 are expressed and released in the TME, where they play a role in the tumor progression." (PMID 40001923, 2025). "Thrombospondin-1, as one of the ligands of CD47, typically inhibits tumor angiogenesis by blocking endothelial cell proliferation and chemotaxis." (PMID 38398223, 2024). "First, they are involved in modulating the expression of thrombospondin-1 (TSP-1), a tumor suppressor and an antiangiogenic regulator." (PMID 39588149, 2024). "In short, we report the first case of recurrent laryngeal IMT in a 24-year-old patient with a novel THBS1::ALK1 fusion, emphasizing the significance of correlating molecular findings with tumor morphology and recurrent behavior." (PMID 39171208, 2024). "Formation of the Annexin A6/LDL receptor-related protein 1/thrombospondin 1 (ANXA6, SE = 3.9/LRP1, SE = 2.5/THBS1, SE = 6.8) complex was restricted to CAFs and required physio-pathologic culture conditions that improved tumor cell survival and migration." (PMID 38892190, 2024). "Generally, THBS1 was primarily found in fibroblasts, endothelial cells, and mononuclear macrophage cells, THBS3 was mostly expressed in fibroblasts, tumor cells and T cells, whereas THBS2, THBS4 and COMP were mainly found in fibroblasts." (PMID 38827236, 2024). "We found that FGF7+/THBS1+ myofibroblasts, MS4A4A+ macrophages, and ZEB1+ endothelial cells were tumour‐enriched cell subtypes in MCA, contributing to MCA progression through crosstalk with MUC1+ cancer cells." (PMID 38778448, 2024). "In tumor microvasculature, CD36 binds to thrombospondin-1 (TSP-1), mediating endothelial cell apoptosis within tumor vasculature." (PMID 39640883, 2024). "In the iCCA TME, we previously demonstrated that THBS1 and THBS2 are mainly expressed and released by CAFs and only to a lesser degree by tumor cells." (PMID 38339060, 2024). "For myofibroblasts, two subsets of this cell cluster (myoFib‐1 and myoFib‐2) were significantly upregulated in tumour tissues, and many oncogenes and CAF canonical genes showed high expression in the myoFib‐1 subset, especially the genes of FGF7 and THBS1." (PMID 38778448, 2024). "In a mass spectrometry-based secretome analysis, THBS1 was one of the dominant proteins induced by TGFβ and released into the ECM by tumor cells." (PMID 39304722, 2024). "THBS1 is a tumor-specific ECM protein, which is expressed mainly in the tumor microenvironment by stromal cells." (PMID 38275880, 2024). "Two sets of genes were chosen, PDGFRA, Lin28A, THBS1, JUN, PLCB1 and GABRA5, which were found to be up- and down-regulated, respectively, in support of tumour cell proliferation." (PMID 38000389, 2024). "PPARα triggers the caspase pathway by up-regulating thrombospondin-1 (TSP-1) expression, and, therefore, results in apoptosis of endothelial cells, angiogenesis inhibition, as well as downregulation of tumor progression." (PMID 36831316, 2023). "The relationship between methylation and expression of genes GSK3B, THBS1, and PTPN1 manifested a positive correlation in most tumour types, whereas this was reversed for genes PPP1R14D." (PMID 37815881, 2023).
tumor (continued). "The most enriched glycoproteins in tumour ECM compared to non-tumour ECM included thrombospondin-2 (16.9-fold), MXRA5 (14.4-fold), peroxidasin (2.5-fold), thrombospondin-1 (2.5-fold), SPARC (2.3-fold), FRAS1 (2.3-fold) and tenascin-C (2.1-fold)." (PMID 37397358, 2023). "Among the monocyte clusters, Mono_2 cluster derived from the tumor tissue (VCAN, THBS1, and CCL20) was found to play an important immunosuppressive role." (PMID 37533434, 2023). "VCAN, THBS1, and CCL20 were highly expressed in the Mono_2 cluster, which was derived from tumor tissue, indicating the potential of this specific monocyte cluster to exert a critical immunosuppressive effect." (PMID 37533434, 2023). "To further assess cellular subpopulation contribution to THBS1 expression, we performed single-cell sequencing analysis of biopsy samples from HFC and LFC tumour regions." (PMID 37138086, 2023). "Isolation and profiling of the metastases core revealed which of the cells enriched in metastasis lesions (compared with distal normal tissues) were concentrated in the tumor core (e.g., Treg, PMN-MDSCs, Mon Thbs1, Mac Isg20)." (PMID 37756565, 2023). "Therefore, THBS1+ monocytes may function as MDSCs that are involved in tumor immune suppression." (PMID 37743226, 2023). "THBS1 and CD47 also jointly participate in anti-tumor immunosuppressive effects, where upregulated expression of THBS1-CD47 not only accelerates the progression of EMT, but also induces fibrosis and inflammation." (PMID 37905960, 2023). "The study also found that treatment with gefitinib increased the tumor suppressor protein thrombospondin-1 (TSP-1) secretion, which can inhibit tumor angiogenesis and promote apoptosis." (PMID 37174117, 2023). "Based on our work, we further identified THBS1 as the potential target gene of METTL14 and functions as the tumor suppressor in PCa." (PMID 35354789, 2022). "miR-467 targets thrombospondin-1 (TSP-1) and regulates the processes of cancer inflammation, promoting inflammation by the recruitment of tumor macrophages and fastening tumor growth connected with high blood glucose influence on angiogenesis processes." (PMID 36555323, 2022). "The high expression of CD36, THBS1, and PDK4 in cancer is related to poor prognosis and promotes tumor progression." (PMID 36147333, 2022). "For example, endothelial-derived thrombospondin-1 (TSP-1) and osteopontin secreted by osteoblasts, as well as matrigel, commonly used for cultured cells in vitro, can induce tumor cell dormancy." (PMID 36237333, 2022). "Thrombospondin-1 (TSP) is a secreted glycoprotein that is also a ligand of CD47; it is a known gatekeeper of tumor progression that sometimes has opposite effects." (PMID 36429020, 2022). "In this study, genes including THBS1, CDKN1A, FBN1, TGFB1, and IGFBP3 were found to be downregulated in tumor cell lines." (PMID 35340229, 2022). "Aberrant THBS1 methylation in tumor tissues and pairing PPLF or serum was closely related to peritoneal dissemination, tumor progression, and poor prognosis (all p < 0.0001)." (PMID 34390026, 2021). "Conversely, TIMP3 (P = 0.0156), THBS1 (P = 0.0156), and CAV1 (P = 0.0313) were all decreased in tumour stroma EVs compared to normal stroma EVs." (PMID 34596356, 2021). "We found that CYP7A1, GINS2, and PDLIM3 were significantly up-regulated, and MYC, MAMDC4, ADAMTS1, THBS1, and RASD1 were significantly down-regulated in HCC tumor samples compared to normal samples." (PMID 34777484, 2021). "Thrombospondin-1 (TSP1) was one of the first anti-angiogenic factors whose expression was decreased during transformation and tumor growth." (PMID 33968943, 2021). "As we aimed to identify potential biomarkers for diagnostic purposes in vitro and to assess these markers in vivo, we investigated the QSOX1, THBS1 and EDIL3 levels in blood plasma obtained from patients 1–3 prior to tumour resection." (PMID 33802764, 2021).
tumor (continued). "All six proteins are differentially expressed in malignant vs. healthy tissue in CRC (FBLN1, MMP3, ACTN4, THBS1, EDIL3) or other tumour entities (QSOX1)." (PMID 33802764, 2021). "NETs promote tumor metastasis by degrading thrombospondin-1 (TSP-1), a secreted extracellular matrix protein that inhibits tumor metastasis." (PMID 34758877, 2021). "In this study, the detection of THBS1 methylation in GC was feasible, with highly consistent levels of THBS1 methylation detected in serum, PPLF, and tumor tissues in the same patient." (PMID 34390026, 2021). "Intriguingly, THBS1 methylation was detected in DNAs extracted from preoperative serum samples in GC patients, which was highly consistent with THBS1 methylation results detected in PPLF and tumor tissues in the same patient." (PMID 34390026, 2021). "These phenotypes are likely due to the misregulation of multiple transcripts coding for adhesion molecules and especially to the downregulation of THBS1 mRNA via SMD and protein in tumor cells." (PMID 35008641, 2021). "We found that CYP7A1, GINS2, and PDLIM3 were significantly up-regulated, and MYC, MAMDC4, ADAMTS1, THBS1, and RASD1 were significantly down-regulated in HCC tumor samples compared with normal samples using the TCGA dataset." (PMID 34777484, 2021). "The close proximity of skeletal vascular networks and hepatic niches favors a microenvironment rich in ECM proteins, secreted factors like THBS1, Stem cell factor (SCF-1) or the chemokine CXCL12 that sustain tumor dormancy." (PMID 33738282, 2021). "On the other hand, the insertion of endostatin and thrombospondin-1 genes in HSV-Endo and T-TSP-1 (both are HSV) destroys tumor vasculature." (PMID 33546172, 2021). "We also found GSC stemness-related genes, SOX2 and ID1, and MES subtype-related genes, THBS1 and CD44, enriched in the core of the tumours, together with higher TRIM28 expression." (PMID 34500575, 2021). "Mature endothelial cells express thrombospondin-1 (TSP-1), which then maintains quiescence of disseminating tumor cells (DTCs) in the lung or bone marrow." (PMID 33807533, 2021). "Based on the RNA-seq data, we observed that genes that suppress tumor angiogenesis, including SERPINE1, THBS1, SERPINB5, CD82 and ANGPTL4, were upregulated." (PMID 32106543, 2020). "Our present finding shows that Axl suppression of tumor cells by knockdown or BGB324 contributes to decreased secretion of factors known to promote angiogenesis, including thrombospondin-1, endothelin-1, uPA and VEGF." (PMID 31080559, 2019). "The perivascular niche in particular has been suggested to influence the fate of DTC by modulation of the expression of Thrombospondin-1 (supporting dormancy) and TGF-β1 and periostin (promoting tumour growth)." (PMID 31236323, 2019). "When breast cancer cells are localized in the microvasculature of the BM, they are facilitated by endothelial cells that produce thrombospondin-1 (TSP-1), a tumor suppressing ant-angiogenic factor that induces quiescence." (PMID 31817646, 2019). "KSHV miRNA suppressed the expression of thrombospondin 1 (THBS1), strong tumor suppressor, and anti-angiogenic factor." (PMID 32038626, 2019). "Thrombospondin-1 (THSB1) is a component of the ECM with a role in regulating cancer development and tumour vasculature." (PMID 30850588, 2019). "Therefore, we further emphasized our speculation that the concomitant up-regulation of MMP9 and THBS1 found in the LNCaP-MST cells may be due to MDM2 overexpression that can easily lead to the acquisition of aggressive tumor phenotype with increased metastatic potential." (PMID 29748481, 2018). "Thrombospondin 1 and 2, also overexpressed in PDAC tumours, are adhesive glycoproteins that mediate cell-to-cell and cell-to-matrix interactions." (PMID 30404163, 2018). "From then, the role of THBS1 as an inhibitor of angiogenesis and tumor progression and the use of THBS-based therapies to inhibit tumor growth has been reported." (PMID 29190912, 2017).